HNRNPUL1 (heterogeneous nuclear ribonucleoprotein U like 1)
Description:
Acts as a basic transcriptional regulator. Represses basic transcription driven by several virus and cellular promoters. When associated with BRD7, activates transcription of glucocorticoid-responsive promoter in the absence of ligand-stimulation. Also plays a role in mRNA processing and transport. Binds avidly to poly(G) and poly(C) RNA homopolymers in vitro.
Synonyms: E1B-AP5; E1BAP5; HNRPUL1; FLJ12944
Tractability: PROTAC: UniProt records ubiquitination sites on it; ubiquitination databases record sites on it; its protein half-life has been measured.
Safety:
Unwanted effects reported when the protein is acted on. In parentheses: how it was acted on, where the effect was seen, and who reports it.
coronary artery disease (source: ClinPGx)
Gene: Protein-coding gene on chromosome 19 (41,262,496 to 41,307,787, forward strand). Ensembl gene ENSG00000105323.
Subcellular location: Nucleus
Subcellular location (Human Protein Atlas): Nucleoplasm
Pathways (Reactome):
Disease: Dengue Virus-Host Interactions
Gene Ontology:
Molecular function: enzyme binding; protein binding; RNA binding
Biological process: alternative mRNA splicing, via spliceosome; response to virus; RNA processing
Cellular component: nucleoplasm; nucleus; synapse
Genetic constraint (gnomAD): Loss-of-function variants: 12 observed, 97.28 expected, observed/expected ratio (o/e) 0.12, 90% interval 0.078 to 0.2. The upper end of that interval is the gene's LOEUF score, 0.2, which puts it in group 1 of 6, group 1 being the genes least tolerant of losing a copy. Missense variants: 790 observed, 1,121.4 expected, observed/expected ratio (o/e) 0.7, 90% interval 0.66 to 0.75. Synonymous variants: 416 observed, 420.87 expected, observed/expected ratio (o/e) 0.99, 90% interval 0.91 to 1.07.
Homologues: Orthologues: chimpanzee HNRNPUL1 (99% identical), macaque HNRNPUL1 (99% identical), dog HNRNPUL1 (98% identical), rabbit HNRNPUL1 (96% identical), rat Hnrnpul1 (96% identical), mouse Hnrnpul1 (95% identical), pig HNRNPUL1 (94% identical), tropical clawed frog hnrnpul1 (53% identical). Paralogues in human: HNRNPU (41% identical), HNRNPUL2 (35% identical).
Diseases named in the same sentence as HNRNPUL1 in open-access papers:
HNRNPUL1 is named in the same sentence as 19 diseases in open-access papers, as found by Europe PMC text mining. Sharing a sentence is not in itself a finding about the gene and the disease. The quoted sentences say what the papers report.
cervical cancer (4 papers, 2023 to 2025). A primary or metastatic malignant neoplasm involving the cervix. "Next, we analyzed the association between HNRNPUL1 expression in cervical cancer and patient prognosis using public clinical databases." (PMID 37484809, 2023). "Loss of HNRNPUL1 suppresses the division, invasion, and migration of cervical cancer cells." (PMID 39764566, 2025). "Furthermore, we identified that expression of HNRNPUL1 is positively associated with expression of NAT10 in cervical cancer and that overexpression of HNRNPUL1 could rescue NAT10 knockdown-mediated tumor inhibition." (PMID 37484809, 2023). "This study indicates that NAT10 enhances the stability of HNRNPUL1 mRNA via ac4C modification, thereby promoting the progression of cervical cancer." (PMID 39764566, 2025). "Recent evidence shows that the target of NAT10 in cervical cancer is heterogeneous nuclear ribonucleoprotein U like 1 (HNRNPUL1)." (PMID 38233930, 2024). "In conclusion, NAT10 enhances the stability of HNRNPUL1 mRNA through ac4C modification, promoting the development of cervical cancer." (PMID 38233930, 2024). "The NAT10 protein regulates HNRNPUL1 expression in cervical cancer cells by catalyzing ac4C formation and increasing the stability of HNRNPUL1 mRNA." (PMID 38233930, 2024). "In conclusion, we show that ac4C modification by NAT10 promotes HNRNPUL1 mRNA stability and accelerates cervical cancer progression." (PMID 37484809, 2023). "Kaplan-Meier Plotter demonstrated that expression of HNRNPUL1 was negatively correlated with Progression-free survival (PFS) in patients with cervical cancer." (PMID 37484809, 2023). "Combined RNA-seq and acRIP-seq analysis revealed HNRNPUL1 as the target of NAT10 in cervical cancer." (PMID 37484809, 2023). "In contrast, the knockdown of NAT10 suppressed the migration and invasive potential of cervical cancer cells, but the up-regulation of HNRNPUL1 partially reversed these effects." (PMID 37484809, 2023). "HNRNPUL1 overexpression partially restored cellular function in cervical cancer cells with NAT10 knockdown." (PMID 37484809, 2023). "The outcomes demonstrated that expression of HNRNPUL1 was higher in cervical cancer compared to normal cervical epithelial tissue." (PMID 37484809, 2023). "NAT10 mediates HNRNPUL1 ac4C acetylation to promote cervical cancer progression." (PMID 39640362, 2024). "Furthermore, depletion of HNRNPUL1 suppressed the cell division, invasion, and migration of cervical cancer." (PMID 37484809, 2023). "Therefore, we selected HNRNPUL1 as the target gene of NAT10 in cervical cancer.RNA-Seq reads were then plotted and visualized in the Integrative genomics viewer (IGV) browser." (PMID 37484809, 2023). "Combining multi-omics and bioinformatics analyses, we found that NAT10-mediated ac4C acetylation may affect the stability and expression of HNRNPUL1 mRNA in cervical cancer cells." (PMID 37484809, 2023). "These outcomes indicate that HNRNPUL1 is an oncogenic factor during cervical cancer development." (PMID 37484809, 2023). "Furthermore, an analogous trend was detected in the colony formation assay, suggesting that HNRNPUL1 knockdown inhibits the abilities of cell growth and colony-forming in cervical cancer cells." (PMID 37484809, 2023). "Thus, this study demonstrates that NAT10 contributes to cervical cancer progression by enhancing HNRNPUL1 mRNA stability via ac4C modification, and NAT10-ac4C-HNRNPUL1 axis might be a potential target for cervical cancer therapy." (PMID 37484809, 2023). "In cervical cancer, NAT10 overexpression induces HNRNPUL1 and DDR1 mRNA expression by promoting acetylation, enhancing tumor proliferation, invasion, and metastasis." (PMID 38233930, 2024). "Therefore, further investigation is warranted to determine whether HNRNPUL1, whose expression is up-regulated by NAT10, may either cause disordered DNA damage repair or promote HPV viral DNA synthesis and infection, thereby exacerbating cervical cancer progression." (PMID 37484809, 2023).
amyotrophic lateral sclerosis (1 paper, 2026). Amyotrophic lateral sclerosis (ALS) is a neurodegenerative disease characterized by progressive muscular paralysis reflecting degeneration of motor neurons in the primary motor cortex, corticospinal tracts, brainstem and spinal cord. "In a small number of amyotrophic lateral sclerosis patients, we identify rare coding variants in the HNRNPUL1 gene, which alter the ability of hnRNPUL1 to bind nucleotides, RNAs, and FUS." (PMID 41971996, 2026).
asthma (1 paper, 2021). "Many key lncRNAs implicated in ABPA and asthma were identified, respectively, i.e., AL139423.1-201, AC106028.4-201, HNRNPUL1-210, PUF60-218 and SREBF1-208." (PMID 34221710, 2021).
autism (1 paper, 2021). Persistent deficits in social interaction and communication and interaction as well as a markedly restricted repertoire of activity and interest as well as repetitive patterns of behavior. "Previously, it was suggested that missense variation in HNRNPUL1 contributes to “high-functioning” autism, meaning an autism diagnosis and IQ in the normal range, which our data support." (PMID 33874999, 2021).
colon cancer (1 paper, 2022). "Our findings indicated that DEDD2, GTF2H5, SNRPA1, BICD1, CELF1, and CLK3 were prognostic risk factors for colon cancer, while ADAD1, CMTR1, HNRNPUL1, FTSJ3, WDR43, THUMPD3, SNRPF were prognostic protective factors." (PMID 36212157, 2022).
esophageal squamous cell carcinoma (1 paper, 2023). Esophageal squamous cell carcinoma (ESCC) is a type of esophageal carcinoma (EC) that can affect any part of the esophagus, but is usually located in the upper or middle third. "HNRNPUL1 suppresses cisplatin (CDDP) sensitivity of esophageal squamous cell carcinoma cells by regulating the formation of MAN1A2, a cyclic RNA (circRNA) that suppresses CDDP sensitivity." (PMID 37484809, 2023).
Failure to thrive (1 paper, 2021). Failure to thrive (FTT) refers to a child whose physical growth is substantially below the norm. "HNRNPUL1-related disorder consists of DD/ID, although about half as often as with HNRNPU variation, short stature, motor and speech delay, structural brain, skeletal, and cardiac abnormalities, abnormal gait, ASD, failure to thrive, and hypertonia." (PMID 33874999, 2021).
melanoma (1 paper, 2024). A malignant, usually aggressive tumor composed of atypical, neoplastic melanocytes. "CPEB4 plays a role in modulating the proliferation and metastasis of melanoma cells, and HNRNPUL1 is implicated in regulating tyrosine kinases linked to aberrant tyrosine metabolism in melanoma." (PMID 39771522, 2024). "Of these, we focused our analysis on three targets known to be associated with melanoma, CPEB4, RPN1, and HNRNPUL1." (PMID 39771522, 2024). "Simultaneously, three of these proteins intersected with established melanoma-related targets, namely RPN1, CPEB4, and HNRNPUL1." (PMID 39771522, 2024). "The association of HNRNPUL1 with tumours has not yet been investigated; however, it has been linked to tyrosine kinases, which may subsequently govern the growth and spread of melanoma cells." (PMID 39771522, 2024). "This study elucidated that L-Shikonin may regulate melanoma-specific markers, melanosomes, tyrosine kinases related to abnormal tyrosine metabolism, and melanoma through multiple targets such as CPEB4 and HNRNPUL1." (PMID 39771522, 2024).
non-small cell lung carcinoma (1 paper, 2023). A group of at least three distinct histological types of lung cancer, including non-small cell squamous cell carcinoma, adenocarcinoma, and large cell carcinoma. "It induces homologous recombination DNA repair, by interacting with BRCA1 and hnRNPUL1, in Non-small cell lung cancer." (PMID 37509693, 2023).
synovial sarcoma (1 paper, 2016). "In total, a group of 42 cases are discovered with MEF2D rearranged to BCL9, CSF1R, DAZAP1 (DAZ (deleted in azoospermia)-associated protein 1), HNRNPUL1 (heterogeneous nuclear ribonucleoprotein U-like 1), SS18 (synovial sarcoma translocation, chromosome 18) or FOXJ2 (Forkhead Box J2)." (PMID 27824051, 2016).
uterine corpus endometrial carcinoma (1 paper, 2020). A endometrial carcinoma (disease) that involves the body of uterus. "HNRNPM, HNRNPUL1, and HNRNPL showed high mutation frequencies, and most hnRNP genes were frequently mutated in uterine corpus endometrial carcinoma (UCEC)." (PMID 32915499, 2020).
cancer (3 papers, 2018 to 2023). A tumor composed of atypical neoplastic, often pleomorphic cells that invade other tissues. "Pan‐cancer genetic alternations of hnRNP genes indicated that the overall average mutation frequency ranged from 0% to 14.9%, and hnRNP genes including HNRNPM, HNRNPUL1, HNRNPL showed high mutation frequencies." (PMID 32915499, 2020). "The ac4C modification enhances HNRNPUL1 mRNA stability and upregulates its expression in CC.These findings contribute to our understanding of the NAT10-ac4C-HNRNPUL1 for tumorigenesis of CC, meanwhile it might be potential target forcervical cancer therapy." (PMID 37484809, 2023). "HNRNPs participated in cancer‐related pathways including protein secretion, mitotic spindle, G2/M checkpoint, DNA repair, IL6/JAK/STAT3 signal and coagulation, of which hnRNP genes of HNRNPF, HNRNPH2, HNRNPU and HNRNPUL1 are more likely to be implicated." (PMID 32915499, 2020). "Interestingly, some of the splicing factors were also affected by paclitaxel, such as hnRNPUL1 for example, indicating that paclitaxel might also inhibit cancer cell growth through modulating RNA AS." (PMID 29706628, 2018).
infection (2 papers, 2021 to 2023). The state of being infected such as from the introduction of a foreign agent such as serum, vaccine, antigenic substance or organism. "Similarly, knockdown of Hnrnpul1 resulted in 81% and 76% reduction of mRNA levels at day 6 post-infection with shUL1#1 and #2, respectively." (PMID 34082786, 2021).
HNRNPUL1 also shares sentences with these, for which no sentence is quoted: tumor (3 papers); leukaemia (2); viral infection (2); myocardial infarction (1); scoliosis (1); T-cell lymphoma (1).